CBLL1 (Cbl proto-oncogene like 1)
Diseases named in the same sentence as CBLL1 in open-access papers (continued):
Sharing a sentence is not in itself a finding about the gene and the disease.
tumor (21 papers, 2017 to 2025). "CBLL1 is significantly upregulated in left-sided tumours, which are associated with a better prognosis." (PMID 38339195, 2024). "The Hakai protein, encoded by the human CBLL1 gene, induces the ubiquitination and degradation of E-cadherin and, as a consequence, its disappearance at cell–cell contacts, impacting tumour progression and metastasis." (PMID 38339195, 2024). "Indeed, 0.986% mutations were found in CBLL1, and only 0.44% corresponded to CBLL1 mis-sense mutations in all types of tumours." (PMID 38339195, 2024). "Moreover, single-sample gene set enrichment analysis (ssGSEA) demonstrated that low CBLL1 expression increased the occurrence of tamoxifen resistance and tumor-associated hypoxia." (PMID 33926554, 2021). "Regarding protein expression, varying intensities of METTL3, METTL14 and CBLL1 staining was observed in the nuclei of tumour epithelial cells by IHC." (PMID 41310336, 2025). "IHC analysis of ~2500 BCa tumour specimens revealed an association of increased METTL14 and CBLL1 with favourable clinical outcomes in BCa and increased METTL3 expression with poor clinical outcomes in hormone receptor negative BCa." (PMID 41310336, 2025). "Multivariate Cox regression analyses were conducted to assess the independent prognostic value of METTL3, METTL14 and CBLL1 expression whilst accounting for the potential confounding variables of nodal stage, tumour size, patient age, ER status and LVI." (PMID 41310336, 2025). "Using bioinformatic methods, we have analysed CBLL1 expression on a large integrated cohort of primary tumour samples from CRC patients." (PMID 38339195, 2024). "This surprising result indicates that high CBLL1 expression was significantly associated with shorter OS and therefore associated with poor prognosis in CMS2 tumours." (PMID 38339195, 2024). "More importantly, CMS2 patients with high CBLL1 expression and poor survival showed the worst prognosis (as observed for CMS4 tumours), highlighting CBLL1 expression as a marker of CMS2 patients with truly poor prognosis." (PMID 38339195, 2024). "In conclusion, our results underline that CMS2 patients with high CBLL1 expression and poor survival showed the worst prognosis (like CMS4 tumours), further highlighting CBLL1 expression as a clear marker of CMS2 patients with worse prognosis." (PMID 38339195, 2024). "By searching for these genes in the PubMed database, it is found that the mechanisms of hsa-miR-455-3p and CBLL1 in tumor progression or studies related to tumor progression have been reported." (PMID 36313417, 2022). "CircRNA-ZFR participated in the negative regulation of miR-545-3p, which induced the isochronous expression with CBLL1 thereby achieving enhancing cisplatin resistance of NSCLC tumor cells in vivo and in vitro." (PMID 35186956, 2021). "Circ_0072083 depletion contributed to DDP-triggered inhibition of NSCLC tumor through miR-545-3p/CBLL1 axis." (PMID 32190002, 2020). "Furthermore, CMS2 patients with high CBLL1 expression and poor survival showed the worse OS, as did tumour samples that were classified as CMS4." (PMID 38339195, 2024). "In addition, we further analysed the association between CBLL1 expression and the site of origin of the CRC tumours." (PMID 38339195, 2024). "Importantly, CMS2 patients with high CBLL1 expression displayed worse overall survival (OS), which is similar to that associated with CMS4 tumours." (PMID 38339195, 2024). "When we analysed the CBLL1 mRNA expression considering the whole cohort of CRC patients (including all CMSs), we found that higher CBLL1 expression was associated with longer OS, further supporting the fact that patients with CMS2 tumours have a good prognosis." (PMID 38339195, 2024). "Recent studies have shown that CBLL1 interacts with E-cadherin phosphorylated by Src kinase to induce ubiquitination and endocytosis of E-cadherin in HCC, which is associated with the transformation of aggressive phenotypes of tumor cells." (PMID 35223847, 2022).
tumor (continued). "Targeted knockdown of CBLL1 inhibits the growth of tumor cells, which may be the potential mechanism of CBLL1 overexpression that is related to poor prognosis in this study." (PMID 35223847, 2022). "Of course, further experiments are needed to verify whether CBLL1 can regulate the malignant phenotype of tumor cells." (PMID 33926554, 2021). "There was a higher abundance of CBLL1 in NSCLC tissues relative to matching non-tumor tissues." (PMID 32190002, 2020). "In addition, we show that CMS2 tumours with higher CBLL1 expression may be used for the stratification of cancer patients with a poor overall survival (OS)." (PMID 38339195, 2024). "Interestingly, CBLL1 is significantly upregulated in left-sided tumours, which have a better prognosis in late stages (III and IV) and tend to have liver and lung metastases, than in right-sided tumours, which tend to have a worse prognosis with frequent peritoneal carcinomatosis." (PMID 38339195, 2024). "Furthermore, UALCAN revealed that the gene expression differences in METTL3, RBM15, RBM15B, VIRMA and CBLL1 may also be related to tumor grade." (PMID 35223847, 2022). "We wondered whether miR-545-3p played an anti-tumor role through targeting CBLL1 in NSCLC." (PMID 32190002, 2020). "Hakai (CBLL1) is an E3 ubiquitin–ligase that induces the ubiquitination and degradation of E-cadherin, inducing epithelial-to-mesenchymal transition (EMT), tumour progression and metastasis." (PMID 38339195, 2024). "The results demonstrated that CBLL1, ELAVL1 and YTHDF1 expressed more in tumor samples than in normal samples of LUAD and LUSC patients, while the expression level of ZC3H13 in tumor samples is lower than in normal samples of LUAD and LUSC patients." (PMID 36261786, 2022). "Except for ZC3H13, the other three genes (CBLL1, ELAVL1 and YTHDF1) were positively correlated with purity state of tumor cell in LUSC." (PMID 36261786, 2022). "Paradoxically, we found that tumor suppressors were negatively correlated with the infiltration of pDCs, DCs, and cytotoxic cells, and the tumor promoters METTL3, VIRMA, and CBLL1 were positively correlated with Tcm and Th2 cell infiltration." (PMID 35223847, 2022). "Our data show that seven m6A regulators (CBLL1, ELAVL1, LRPPRC, RBM15B, YTHDF1, YTHDF2, and ZC3H13) are related to tumorigenesis, tumor microenvironment and tumor prognosis." (PMID 33670062, 2021). "Particularly, in contrast to their low CNV frequencies (< 5%) in normal samples, CBLL1, METTL14, RBM15, IGF2BP1, YTHDC1, and YTHDF2 exhibited more than 20% difference in their frequencies of CNVs between tumor and normal samples." (PMID 33585234, 2020). "However, only CBLL1 was also found to be an independent prognostic indicator of BCSS, TTDM and DFS when considering the potential confounding variables of nodal stage, tumour size, patient age, ER status and LVI." (PMID 41310336, 2025). "We decided to investigate whether high CBLL1 expression in CMS2 patients could be a biomarker for worse prognosis and whether it was comparable to the survival observed in CMS4 tumours." (PMID 38339195, 2024). "METTL3, METTL14, WTAP and CBLL1 were expressed at the protein level in both non-malignant prostate and tumour tissue." (PMID 36733939, 2022). "In a similar manner, CBLL1 gene expression was associated with non-mutant BRAF samples when analysing 205 samples of CRC patients (20 tumour samples with BRAF mutations and 195 tumour samples with non-mutated BRAF)." (PMID 38339195, 2024). "The results showed that expression levels of METTL3, VIRMA and CBLL1 were significantly increased, while expression levels of METTL14 and ZC3H13 were significantly decreased in HCC, which was closely related to clinicopathological factors, such as tumor stage and prognosis." (PMID 35223847, 2022).
tumor (continued). "Interestingly, using a cohort of 205 samples of CRC patients, including 85 tumour samples with KRAS mutations and 120 tumour samples with KRAS wild type (non-mutated), we detected an association of CBLL1 gene expression with non-mutant KRAS samples, as shown in the boxplot." (PMID 38339195, 2024).
cancer (14 papers, 2012 to 2025). A tumor composed of atypical neoplastic, often pleomorphic cells that invade other tissues. "Considering also the functional context in cancer, Hakai (CBLL1 gene) has been implicated in tumour progression and metastasis through a possible role in the EMT programme." (PMID 38339195, 2024). "Taken together, these results suggest a possible role for CBLL1 in the formation and/or maintenance of cancer stem cell tumourspheres." (PMID 38339195, 2024). "CBLL1 mRNA levels are highly upregulated in cancer stem cell tumoursphere-derived HCT116 compared to HCT116 monolayer cell culture." (PMID 38339195, 2024). "These mRNA levels are highly upregulated in cancer tumourspheres, while CBLL1 silencing shows a clear reduction in tumoursphere size and in stem cell biomarkers." (PMID 38339195, 2024). "To gain a comprehensive view of the potential effect of the differential gene expression of CBLL1 assigned to CMS2, we focused our attention on the potential new role of CBLL1 in regulating cancer stem cell properties." (PMID 38339195, 2024). "We then tested the effect of CBLL1 silencing on HT29 cancer stem cell tumourspheres using a previously reported inducible system of viral transduction of shRNA-CBLL1 silencing." (PMID 38339195, 2024). "Taken together, these findings suggest that the oncogenic functions of CBLL1 identified in other cancer types are also relevant to PCa." (PMID 36733939, 2022). "This is supported by reports of increased expression of CBLL1 in other cancer types and that CBLL1 knockdown results in arrested cell cycle and reduced cellular proliferation." (PMID 36733939, 2022). "Whilst CBLL1 is known to regulate E-cadherin, a protein with a key role in the development of cancer, little is known about the role of CBLL1 in carcinogenesis." (PMID 36733939, 2022). "Moreover, CBLL1 silencing on cancer stem cell tumourspheres induces a significant reduction in tumoursphere size, which is accompanied by the downregulation of the stem cell biomarkers LGR5 and c-MYC at both mRNA and protein levels." (PMID 38339195, 2024). "Furthermore, the high CBLL1 expression observed in the tumourspheres was accompanied by the upregulation of other established cancer stem cell markers, including LGR5, NANOG, SOX2, KLF4 and c-MYC mRNA levels." (PMID 38339195, 2024). "In addition, a higher expression of Hakai and Lgr5 proteins was detected in cancer stem cell tumourspheres, while CBLL1 silencing reduces the tumoursphere size and downregulates the Lgr5 biomarker." (PMID 38339195, 2024). "Therefore, CBLL1 could be a suitable and attractive target for new cancer therapies." (PMID 33926554, 2021). "CBLL1 silencing was confirmed at the mRNA level, and mRNA downregulation of other known stem cell markers including LGR5, NANOG and c-MYC was also detected in sh-CBLL1 HT29 cancer stem cell tumourspheres compared to sh-control tumourspheres." (PMID 38339195, 2024). "However, CBLL1 and METTL16 have mainly been studied in cancers and act as oncogenic markers to promote the development and progression of tumors." (PMID 36685841, 2022).
CBLL1 also shares sentences with these, for which no sentence is quoted: chronic myeloid leukemia (1 paper); esophageal cancer (1); hepatitis C (1); Human papillomavirus infection (1); infertile (1); ischemic stroke (1); liver cancer (1); mastitis (1); melanoma (1); pancreatic cancer (1); Sepsis (1); viral infection (1).